ACE (angiotensin I converting enzyme)
Diseases named in the same sentence as ACE in open-access papers (continued):
Sharing a sentence is not in itself a finding about the gene and the disease.
Hypertension (continued). "Through the induction of the coagulation cascade (PAI-1, TF, VCAM-1) and vasoregulatory activities (ACE, ET-1) PM2.5-AB transiently augments the hypertension and may contribute to the development and progression of atherosclerotic lesions." (PMID 20920269, 2010). "The South African Hypertension Guideline recommends the following combination treatments for essential hypertension after failure of first-line therapy – diuretic plus an ACE inhibitor, ARB or calcium channel blocker (CCB), and CCB plus ACE inhibitor or ARB." (PMID 19701531, 2009). "Previous studies have focused on the association of any of the ACE, AT1R and AGT gene polymorphisms with coronary events of several degrees, related or not with MI and essential hypertension." (PMID 18637188, 2008). "Those facts suggests that strategies directed to prevent hypertension should be launched in younger rather than in older ages and both prevention of hypertension and its treatment with ACE inhibitors should be focused on families rather than on individuals." (PMID 16509973, 2006). "Strategies directed to prevent hypertension should be launched in younger rather than in older ages and both prevention of hypertension and its treatment with ACE inhibitors should be focused on families rather than on individuals." (PMID 16509973, 2006). "Hypertension risks estimates for AGT and ACE genotypes by gender." (PMID 15642127, 2005). "In accordance with two of them including one German dataset, the present study fails to find an effect of the AGT or ACE genotype on the severity of hypertension." (PMID 15642127, 2005). "In the present study, the AGT TT genotype was negatively correlated to hypertension in women only while no sex-specific effect of the ACE gene was shown." (PMID 15642127, 2005). "Hypertension observed in offspring as a result of maternal high-fructose diet programming correlates with abnormal activation of the classic RAS axis, evidenced by increased levels of PRR, angiotensinogen, ACE, and AT1R in organs that regulate BP, such as the kidneys, blood vessels, and brain." (PMID 39911806, 2025). "This meta‐analysis extends the findings of previous landmark trials, such as the PROGRESS and HOPE trials, which showed the beneficial effects of antihypertensive treatment with ACE‐inhibitors in patients with or at high risk for CVD, even in the absence of hypertension." (PMID 40041991, 2025). "For example, hypertension was common across all levels of kidney function, and patients with reduced kidney function were more likely to have non-commercial insurance and to be prescribed ACE inhibitors/ARBs." (PMID 40386414, 2025). "Additionally, 8 non-FCVs (67%) and 7 FCVs (70%) provide sulphonylureas, and 10 non-FCVs (83%) and 7 FCVs (70%) offer ACE inhibitors for diabetes and hypertension treatment." (PMID 41338627, 2025). "Although routine genetic screening for hypertension is not currently recommended, identifying carriers of risk genotypes such as MTHFR TT or ACE DD could contribute to the development of personalized medicine strategies." (PMID 41301901, 2025). "Emerging research suggests that angiotensin-converting enzyme (ACE) inhibitors and angiotensin II receptor blockers (ARBs), while primarily used to treat hypertension and heart failure, may also benefit OA patients by modulating the renin-angiotensin-aldosterone system (RAAS)." (PMID 41023741, 2025). "Although the guidelines we reviewed do not specifically recommend lisinopril as the ACE inhibitor of choice during breastfeeding, current data suggest that it may be considered as a treatment option for hypertension in breastfeeding mothers." (PMID 40507483, 2025). "Similarly, in the ADMA and TMAO models, resveratrol prevented offspring hypertension by decreasing the expression of ACE and AT1R while enhancing components of the non-classical RAS pathway." (PMID 39339768, 2024).
Hypertension (continued). "Finally, inhibition of ACE did not exert a beneficial effect on either hypertension or altered vascular reactivity, suggesting that RAS was not playing a major role in the pathogenesis of these abnormalities." (PMID 39044930, 2024). "This suggests that the loop involving ACE, ACE2, Ang 1-7, and Th2 responses may be a protective mechanism that helps modulate the pro-inflammatory effects of the activated RAS, thereby reducing vascular damage and hypertension." (PMID 39337863, 2024). "We hypothesize that the combination of an ACE inhibitor with a CCB, compared with the combination of an ACE inhibitor with a thiazide diuretic, is more efficacious in blood pressure lowering and has fewer side effects in the treatment of hypertension." (PMID 38263021, 2024). "Many older people, people with diabetes, and people taking antihypertensive drugs, such as ACE inhibitors and angiotensin II receptor blockers, have difficulty in controlling hypertension and were observed to achieve benefits, without any evidence of harm, in the SSaSS trial." (PMID 38284271, 2024). "In patients with AF, heart failure and hypertension there may be prolongedactivation of the RAAS, resulting in elevated myocardial tissue levels of angiotensin converting enzyme (ACE).There is a resultant up-regulation of ATII receptors which promote inflammatoryresponse and fibrosis." (PMID 39076563, 2024). "In a univariate analysis, ACE levels were increased in patients with sarcoidosis, lymphoma (Hodgkin’s and non-Hodgkin’s), leukemia, cirrhosis, interstitial lung disease, Gaucher’s disease, hypertension, heart failure, and in those not taking ACE inhibitors." (PMID 39768579, 2024). "Additionally, histone modifications of the (pro)renin receptor and ACE, along with specific microRNAs (miR-132, miR-143/145, miR-155, miR-212), regulate BP by targeting the RAS, linking epigenetic changes to kidney disease and hypertension." (PMID 39769369, 2024). "It has been observed that treatment with AGTR1 antagonists significantly reduces the total UPDRS score after one year in PD patients with hypertension, whereas this effect is not observed in patients receiving angiotensin-converting enzyme (ACE) inhibitor treatment." (PMID 38978048, 2024). "Angiotensin I is usually cleaved by angiotensin-converting enzyme (ACE) to generate the active product angiotensin II, which is involved in maintaining blood pressure, body fluid and electrolyte homeostasis, as well as playing a role in the pathogenesis of essential hypertension and preeclampsia." (PMID 39502570, 2024). "Comparative studies between ADPKD patients with hypertension and normal renal function and those with essential hypertension have shown higher levels of plasma aldosterone and renin in ADPKD subjects in orthostatic and clinostatic positions, and after ACE-inhibitor (Captopril) stimulation." (PMID 39200287, 2024). "Thus, the use of ACE inhibitors (ACEI) has become one of the major focuses for the alleviation of hypertension and is considered one of the first-line drugs for treatment of hypertension." (PMID 37174355, 2023). "miR-27a-3p can increase theexpression of angiotensin-converting enzyme (ACE), which leads to cardiovascularinflammation and remodeling by the nuclear factor kappa-light-chain-enhancer of activated B cells (NF-κB) pathway activation, ultimatelyleading to hypertension." (PMID 39076378, 2023). "Considering diabetes and hypertension, two prevalent non-communicable diseases (NCDs) in Iran, antidiabetic medications and ACE inhibitors/ARBs, commonly used to treat hypertension, were associated with a 21% decrease and a 32% increase in the risk of mortality in all cases." (PMID 38164450, 2023). "A clinical trial based on patients with mild to moderate hypertension also discovered that the administration of Benifuuki, whose active ingredient is an EGCG-O-methylated derivative, exerts a hypotensive effect by significantly inhibiting angiotensin I-converting enzyme activity." (PMID 37640837, 2023).
Hypertension (continued). "The angiotensin-converting enzyme (ACE) inhibitor and angiotensin II (Ang II) type I receptor (AT1R) blocker are part of therapeutics for combating CKD progression, as circulating Ang II is reported to promote EC dysfunction and hypertension as well as extracellular matrix (ECM) dysregulation." (PMID 37446114, 2023). "However, the incorporationof an angiotensin-converting enzyme (ACE)-inhibitor or a calcium channel blocker and a statin has consistentlydemonstrated reductions in lipid levels and the number of ASCVD events inpatients with hypertension and lipid disorders." (PMID 39076713, 2023). "One study found that antihypertensive therapy did not improve endothelial function in patients with essential hypertension, while in another study, treatment of hypertension with ACE inhibitors normalized blood pressure and restored vascular reactivity of patients." (PMID 36829839, 2023). "It should be noted that protein hydrolysates and peptides can have a positive impact on the intestinal microbiota (e.g., increased microbial diversity and richness) without, however, having a significant effect on ACE but by affecting other markers of hypertension." (PMID 36557936, 2022). "In recent decades, angiotensin converting enzyme inhibitors (ACE inhibitors), angiotensin receptors blockers (ARBs), direct vasodilators, calcium channel blockers, ganglion blockers, and thiazide type of diuretics are the main clinical drugs in the treatment of hypertension." (PMID 36016567, 2022). "However, although captopril and other ACE inhibitors have been used in medicine for the treatment of hypertension and heart failure for over forty years, hemolysis has not been found to be an adverse effect of ACE inhibitors." (PMID 36232330, 2022). "In a rat model of hypertension induced by the NOS inhibitor L-NAME, pretreatment with ginger rhizomes was shown to lower blood pressure, inhibit the angiotensin-1-converting enzyme (ACE) and arginase activities, and increase vasodilator nitric oxide (NO) levels." (PMID 35585878, 2022). "Antihypertensive peptides (AHTPs) are bioactive peptides obtained from natural foods that have the effects/activities of ACE inhibitors against hypertension and are considered safe for consumption, with fewer adverse side effects than synthetic ACE inhibitor drugs or even no side effects." (PMID 35571042, 2022). "Thus, carriers of the D/D genotype of the male ACE gene (there were 37 people in this sample) and carriers of the −9 genotype of the BDKRB2 gene are recommended to prevent cardiovascular diseases, mainly arterial hypertension." (PMID 36140844, 2022). "Additionally, a dysregulation of the renin–angiotensin system (RAS) pathway has been observed with increased angiotensin-converting enzyme (ACE) activity and higher levels of angiotensin II and aldosterone especially in OSA patients with pre-existing hypertension." (PMID 34834555, 2021). "Among the study groups we enrolled 35 patients affected by arterial hypertension treated with ACE-inhibitors, calcium antagonists, or non-selective beta blocker: 13 in the NAFLD wild type control group, 8 in the NAFLD treated wild type, and 14 in the NAFLD treated mutated one, respectively." (PMID 34692725, 2021). "The results obtained suggest that the peptide RIY may be a useful tool in the treatment of hypertension, especially in cases when ACE inhibitors are not effective." (PMID 34079459, 2021). "Moreover, angiotensin-converting enzyme (ACE) has been shown to be able to degrade Aβ in vitro although animal models suggest that treating hypertension with an ACE inhibitor does not increase the amyloid burden in vivo." (PMID 33498262, 2021). "On this basis, it has been hypothesized that the use of ACE inhibitors and AT1R blockers in the treatment of arterial hypertension during the COVID-19 pandemic may make the patient more susceptible to SARS-CoV-2 infection, and the course of COVID-19 may be more severe." (PMID 33925881, 2021).
Hypertension (continued). "A few flavonoids were shown to suppress the activity of angiotensin-converting enzyme (ACE), which not only plays an important role in cardiovascular diseases such as in hypertension, but may also represent a key determinant in viral infections, and pneumonia." (PMID 32982616, 2021). "Interestingly, human GIVER was upregulated in arteries from hypertensive patients but significantly attenuated in hypertensive patients taking ACE (angiotensin-converting enzyme) inhibitors and angiotensin receptor blockers, supporting a role for GIVER in AngII signaling and hypertension." (PMID 34234740, 2021). "In our analysis, a larger proportion of hospitalized patients reported taking ACE inhibitors and ARBs than non-hospitalized patients, but the difference was not significant after adjusting for several factors, including age and hypertension, in multivariable analysis." (PMID 34473791, 2021). "This demonstrates that affinity purification using Fe3O4@ZIF-90-ACE is a highly efficient method for separating ACE inhibitory peptides from complex protein mixtures and the purified peptide KNFL could be developed as a functional food ingredients against hypertension." (PMID 33807119, 2021). "ACE participates in the renin-angiotensin-aldosterone system (RAAS), which affects salt retention a protein for water balance and blood vessels; therefore, RAAS controls blood pressure, and drugs that inhibit this enzyme are effective in treating high blood pressure." (PMID 34798807, 2021). "(ii) ACE genotypes do not have any impact on obesity and hypertension." (PMID 32408411, 2020). "The age-related decline of renal function varies markedly, due to nephrotoxic effects of comorbidities such as hypertension or diabetes, and drug treatment, particularly with non-steroidal anti-inflammatory drugs (NSAIDs) and angiotensin -converting enzyme (ACE) inhibitors." (PMID 32651902, 2020). "However, the present results may indicate novel therapeutic strategies for patients with CO poisoning using ACE and/or AT1R antagonists, which have been clinically and safely used worldwide for the treatment of hypertension and its complications for years." (PMID 32054947, 2020). "However, ACE inhibitors or ARBs were not included in the multivariate analysis because of their high correlation with hypertension." (PMID 32599972, 2020). "Kinin antagonists also partially reversed their antihypertensive action in rats with renovascular hypertension; however, lack of B2 receptors did not abolish the anti-hypertensive effect of ACE inhibition in mice with renovascular (2 kidney-1 clip or 2K1C) hypertension." (PMID 33126450, 2020). "As the univariate association of ACE inhibitor/ARB usage with CV events was no longer apparent after multivariable adjustment, this is most likely a reflection of treated hypertension or prior congestive heart failure rather than a true adverse effect of these agents." (PMID 32824667, 2020). "It is not surprising that among the inactive compounds we found diuretics, ACE inhibitors, Angiotensin Receptor Blockers and Calcium channel blockers, which are indicated for the treatment of ADPKD-associated hypertension and are not expected to reduce cell proliferation." (PMID 32144367, 2020). "Moreover, patients with hypertension had lower serum ACE activity than patients without hypertension." (PMID 33238910, 2020). "Several categories of antihypertensive drugs, including calcium channel blockers, angiotensin-converting enzyme (ACE) inhibitors, or angiotensin II receptor blockers and ultra-selective β1-blockers such as nebivolol, have been shown to reverse ED in essential hypertensives." (PMID 32718053, 2020). "Although these preliminary findings must be confirmed by further researches with larger sample size, we could observe that the integrative analysis of ACE and ACE2 can be an informative tool in hypertension understanding that needs to be explored in new studies." (PMID 31430320, 2019).
Hypertension (continued). "Angiotensin-converting enzyme (ACE) inhibitors or angiotensin receptor blockers (ARBs) were prescribed to 127 574 adults (20.5%) with CKD, with slightly higher use of these agents among those with CKD and hypertension (112 449 of 434 657 [25.9%]) (eTable 5 in the Supplement)." (PMID 31860111, 2019). "However, a recent meta-analysis was not able to show the association of the SNPs of ACE, AGT, and CYP11B2 genes and hypertension." (PMID 31511791, 2019). "They evaluated the use of concomitant drugs that may potentially affect the thyroid gland, such as ACE inhibitors and beta blockers; however, there was no evaluation of insulin resistance, hyperglycemia, obesity, or hypertension." (PMID 31203592, 2019). "However, when test parameters of H2O2, О2•- and 8-isoprostane were compared within one genotype of the ACE gene, the most significant increase in oxidative stress parameters (compared with controls) was found in patients with COPD+hypertension and the I/I genotype." (PMID 32025262, 2019). "The evaluation of ACE inhibitors or ARBs as negative controls suggested hypertension progression may have tempered the incidence of the prescribing cascade (aSR for ACE inhibitors and ARBs, 1.27; 95% CI, 1.24-1.29)." (PMID 31880802, 2019). "In this study, fosinopril was predicted as the best ACE inhibitor (with maximum binding affinity for ACE after teprotide) to be used as a potentially therapeutic orally active drug (on the basis of Lipinski’s rule of five and BOILED-egg approach) for the treatment of hypertension." (PMID 30875817, 2019). "Whether the effect of ACE-inhibition on coronary microvascular function in some studies is indirectly mediated via treatment of hypertension with no direct effect on the microvasculature is uncertain." (PMID 29883497, 2018). "ACE inhibitory peptides from natural products, especially from medicinal fungi, are increasingly concerned with their prophylactic and therapeutic benefits on hypertension and having no harmful side effects." (PMID 29854760, 2018). "Unfortunately, none of the antihypertensive agentscould significantly reduce perinatal mortality.Continuation of current medication except for angiotensin-converting enzyme (ACE) inhibitors, ARBs,and direct renin inhibitors may be the best strategy incases with pre-existing hypertension." (PMID 29707923, 2018). "Angiotensin-converting enzyme (ACE, 3.4.15.1) plays a crucial role in regulating blood pressure by converting angiotensin І to the octapeptide angiotensin II, a potent vasoconstrictor that is responsible for the development of hypertension, and by degrading the vasodilator bradykinin." (PMID 29973522, 2018). "Angiotensin-converting enzyme (ACE) inhibitors (e.g., Captopril, Lisinopril, Enalapril, Ramipril) and Angiotensin II receptor blockers (ARB) (e.g., Valsartan, Telmisartan, Losartan) are widely used to treat hypertension, which is a typical hyperfunctional disease." (PMID 30448823, 2018). "The study demonstrated for the first time that the ACE inhibitory peptide GAAGGAF from Coix glutelin has a significant antihypertensive effect, and it could be a good natural ingredient for pharmaceuticals against hypertension and the related diseases." (PMID 28098801, 2017). "Since angiotensin-converting enzyme (ACE) inhibitors and calcium antagonists have complimentary mechanisms of action, enalapril, an ACE inhibitor, is used in combination with felodipine, a vascular selective dihydropyridine calcium antagonist, for the treatment of hypertension." (PMID 29050316, 2017). "In addition to pharmacological therapy, such as through angiotensin converting enzyme (ACE) inhibitors or angiotensin receptor blockers (ARB) for proteinuria and/or hypertension control, nutritional interventions have been widely recommended in the management of CKD." (PMID 28362355, 2017).